RRP8 (ribosomal RNA processing 8)
Description:
Essential component of the eNoSC (energy-dependent nucleolar silencing) complex, a complex that mediates silencing of rDNA in response to intracellular energy status and acts by recruiting histone-modifying enzymes. The eNoSC complex is able to sense the energy status of cell: upon glucose starvation, elevation of NAD(+)/NADP(+) ratio activates SIRT1, leading to histone H3 deacetylation followed by dimethylation of H3 at 'Lys-9' (H3K9me2) by SUV39H1 and the formation of silent chromatin in the rDNA locus. In the complex, RRP8 binds to H3K9me2 and probably acts as a methyltransferase. Its substrates are however unknown.
Synonyms: KIAA0409; NML
Tractability: Small molecule: a structure with a bound ligand is known. Antibody: its Gene Ontology location is reachable by antibodies, with high confidence. PROTAC: ubiquitination databases record sites on it; its protein half-life has been measured.
Gene: Protein-coding gene on chromosome 11 (6,595,072 to 6,603,616, reverse strand). Ensembl gene ENSG00000132275.
Subcellular location: Nucleus, nucleolus
Subcellular location (Human Protein Atlas): Cytosol; Nucleoli; Nucleoplasm
Pathways (Reactome):
Gene expression (Transcription): SIRT1 negatively regulates rRNA expression
Gene Ontology:
Molecular function: protein binding; RNA binding; histone H3K9me2/3 reader activity; rRNA (adenine-N1-)-methyltransferase activity; methyltransferase activity
Biological process: cellular response to glucose starvation; energy homeostasis; negative regulation of cell cycle; negative regulation of DNA-templated transcription; rDNA heterochromatin formation; regulation of G1 to G0 transition; regulation of transcription by glucose
Cellular component: chromatin silencing complex; cytosol; eNoSc complex; nucleolus; nucleoplasm; rDNA heterochromatin
Genetic constraint (gnomAD): Loss-of-function variants: 48 observed, 44.78 expected, observed/expected ratio (o/e) 1.07, 90% interval 0.85 to 1.36. The synonymous counts are far from expectation, so gnomAD's model fits this gene poorly and the ratio says little. Missense variants: 651 observed, 573.11 expected, observed/expected ratio (o/e) 1.14, 90% interval 1.06 to 1.21. Synonymous variants: 272 observed, 214.02 expected, observed/expected ratio (o/e) 1.27, 90% interval 1.15 to 1.4.
Homologues: Orthologues: chimpanzee RRP8 (99% identical), macaque RRP8 (94% identical), dog RRP8 (81% identical), guinea pig RRP8 (80% identical), pig RRP8 (79% identical), rabbit RRP8 (78% identical), mouse Rrp8 (76% identical), rat Rrp8 (74% identical), tropical clawed frog rrp8 (39% identical), zebrafish rrp8 (38% identical), Caenorhabditis elegans rrp-8 (25% identical), Drosophila melanogaster CG7137 (25% identical).
Diseases named in the same sentence as RRP8 in open-access papers:
RRP8 is named in the same sentence as 18 diseases in open-access papers, as found by Europe PMC text mining. Sharing a sentence is not in itself a finding about the gene and the disease. The quoted sentences say what the papers report.
liver cancer (3 papers, 2021 to 2024). An epithelial or non-epithelial malignant neoplasm that arises from the liver. "RRP8 expression was closely linked to Th17, DC, NK CD56bright and Th2 cell infiltration in liver cancer." (PMID 38722372, 2024). "Finally, loss of RRP8 expression inhibited liver cancer cells to proliferate and to migrate in vitro." (PMID 38722372, 2024). "Loss of RRP8 inhibited the proliferation of PLC5 and LM3 liver cancer cells, according to the CCK8 assay." (PMID 38722372, 2024). "To further confirm the function of RRP8 in liver cancer, we quantified cell growth after RRP8 knockdown and knockout in PLC5 and LM3 cell lines using doxycycline-inducible shRNAs and single-guide RNAs (sgRNAs), respectively." (PMID 38722372, 2024). "The novel finding indicated that RRP8 was overexpressed in liver cancer specimens and that RRP8 overexpression was correlated with an unfavourable prognosis." (PMID 38722372, 2024). "Our functional studies revealed that both knockdown and knockout of RRP8 dramatically attenuated liver cancer cells to proliferate and migrate." (PMID 38722372, 2024). "Further research indicated that RRP8 might increase the malignancy of liver cancer by activating the MAPK and β-catenin pathways." (PMID 38722372, 2024). "Finally, data from our functional knockdown and knockout experiments revealed that RRP8 is essential for liver cancer cells to proliferate and migrate by inhibiting the MEK1/2 and β-catenin signalling pathways." (PMID 38722372, 2024). "The Western blot results demonstrated that RRP8 was highly expressed in Huh7, MHCC-97H, HCCLM3, HepG2, and PLC5 liver cancer cells." (PMID 38722372, 2024).
hepatocellular carcinoma (2 papers, 2024 to 2025). A malignant tumor that arises from hepatocytes. "Multivariate regression analysis suggested that RRP8 may serve as a potential independent risk factor in hepatocellular carcinoma." (PMID 38722372, 2024). "The elevated expression of m1A methyltransferases (TRMT10C, TRMT6) and ribosomal RNA processing protein 8 (RRP8), along with m5C reader YBX1, demonstrate a significant association with unfavorable prognosis in hepatocellular carcinoma." (PMID 40699703, 2025). "However, the role of RRP8 in hepatocellular carcinoma (HCC) is still uncertain." (PMID 38722372, 2024).
autoimmune disease (1 paper, 2015). A disorder resulting from loss of function or tissue destruction of an organ or multiple organs, arising from humoral or cellular immune responses of the individual to their own tissue constituents. "C57BL/6 mice are not prone to autoimmune disease, but after 7–9 injections with RRP8 or TNP1, they demonstrated proteinuria." (PMID 26098692, 2015).
glomerulonephritis (1 paper, 2015). A renal disorder characterized by damage in the glomeruli. "IC-deposited glomerulonephritis was induced in C56BL/6 mice by repeated stimulation with recombinant human RRP8 or TNP1 protein." (PMID 26098692, 2015). "Therefore, we planned to investigate whether glomerulonephritis would be induced by injecting recombinant mouse RRP8 or mouse TNP1 protein into mice." (PMID 26098692, 2015). "Next, we examined whether IC would be formed by injection of human RRP8 or TNP1 into C57BL/6 mice and whether glomerulonephritis would occur predominantly when IC was formed with RRP8 or TNP1." (PMID 26098692, 2015). "Therefore, we examined whether IC would be formed by injection of human RRP8 or TNP1 into C57BL/6 mice and whether glomerulonephritis would occur predominantly as a result of IC formation with RRP8 or TNP1." (PMID 26098692, 2015).
melanoma (1 paper, 2014). A malignant, usually aggressive tumor composed of atypical, neoplastic melanocytes. "77% of melanoma cases (219 patients) are recognized from healthy controls by the ABSENCE of the rrp8 = (bbabab) allele pattern for (CT318-AG49-CT60-JO30-JO27) SNP cycle." (PMID 24475110, 2014).
nephritis (1 paper, 2015). Inflammation of renal tissue. "Both anti-RRP8 and anti-TNP1 autoantibodies were detected in the sera of MRL/lpr mice that developed nephritis, closely resembling the pattern seen in human LN." (PMID 26098692, 2015). "Among the SLE patients, the positive rate of anti-RRP8 antibody was significantly higher in LN than that in SLE without nephritis (63.6% (n = 7) vs 12.5% (n = 8), respectively; p = 0.00017, odds ratio 12.25, 95% confidence interval 2.9–51.4)." (PMID 26098692, 2015). "Among SLE patients, 63.6% and 45.5% of those with LN were positive for anti-RRP8 and anti-TNP1 antibodies, compared with 12.5% and 9.4% of SLE patients without nephritis, respectively." (PMID 26098692, 2015). "In addition, the positivity rates for both anti-RRP8 and anti-TNP1 autoantibodies were significantly higher in the LN group than in the SLE group without nephritis." (PMID 26098692, 2015).
rheumatic diseases (1 paper, 2015). "ELISA analysis of sera from patients with various rheumatic diseases demonstrated reactivity for RRP8 and TNP1 in 20% and 14.7% of SLE patients, respectively, whereas there was little or no reactivity in patients with other rheumatic diseases." (PMID 26098692, 2015). "We compared the circulating levels of anti-RRP8 and anti-TNP1 antibodies among patients with rheumatic diseases using ELISA." (PMID 26098692, 2015).
vasculitis (1 paper, 2015). "On the other hand, inflammatory changes such as vasculitis and infiltrating inflammatory cells were hardly observed in the lung, liver and spleen of both RRP8-injected and TNP1-injected mice." (PMID 26098692, 2015).
cancer (3 papers, 2021 to 2024). A tumor composed of atypical neoplastic, often pleomorphic cells that invade other tissues. "Ribosomal RNA Processing 8 (RRP8) is a nucleolar Rossman fold-like methyltransferase that exhibits increased expression in many malignant tumours." (PMID 38722372, 2024). "In addition, compared to that in paired normal tissue samples, RRP8 expression was increased in 5 types of cancer." (PMID 38722372, 2024). "Analysis of RRP8 expression across cancers was performed by using multiple databases." (PMID 38722372, 2024). "However, the roles and pathological functions of RRP8 in cancer, especially those in HCC, have yet to be determined." (PMID 38722372, 2024). "RRP8 was found to be overexpressed in 16 types of cancer, including HCC." (PMID 38722372, 2024). "The expression of YTHDF2 in cancer tissues was also up-regulated (p < 0.05), while those of RRP8, YTHDC1, and YTHDF3 were not significantly different." (PMID 34195072, 2021).
tumor (2 papers, 2022 to 2024). "TCGA dataset contained 374 HCC tissues and 50 normal tissues, the expression of RRP8 was significantly elevated in tumor specimens." (PMID 38722372, 2024). "It has been postulated that the activation of the MAPK and β-catenin signalling pathways may play a pivotal role in the progression of RRP8-overexpressing tumours, suggesting that RRP8 may be a potential target for curing HCC." (PMID 38722372, 2024). "Additionally, based on the ROC curve analysis results, we found that RRP8 could serve as an attractive predictive biomarker to distinguish tumour tissues from normal tissues or peritumoral tissues." (PMID 38722372, 2024).
RRP8 also shares sentences with these, for which no sentence is quoted: Obesity (3 papers); breast carcinoma (1); colorectal adenoma (1); fatty liver disease (1); glioma (1); metabolic disease (1); migraine (1); triple-negative breast carcinoma (1).